U3 (Small nucleolar RNA U3 )
Synonyms: LOC124906380
Gene: Small nucleolar RNA gene on chromosome 3 (64,071,807 to 64,072,019, reverse strand). Ensembl gene ENSG00000200222.
Gene Ontology:
Biological process: RNA processing
Cellular component: nucleolus
Homologues: Orthologues: chimpanzee U3 (98% identical), macaque U3 (93% identical), rabbit U3 (54% identical), dog U3 (31% identical), rat LOC120098417 (27% identical). Paralogues in human: SNORD3P1 (82% identical), U3 (81% identical), SNORD3E (80% identical), U3 (80% identical), SNORD3H (78% identical), U3 (78% identical), SNORD3D (77% identical), U3 (77% identical), U3 (76% identical), U3 (75% identical), U3 (74% identical), SNORD3G (74% identical), and 13 more.